GOT2 (glutamic-oxaloacetic transaminase 2)
Diseases named in the same sentence as GOT2 in open-access papers (continued):
Sharing a sentence is not in itself a finding about the gene and the disease.
non-alcoholic fatty liver disease (2 papers, 2016 to 2025). "In addition, a clinical study reported a significant positive correlation between hepatic GOT2 mRNA expression and systolic hypertension in patients with non-alcoholic fatty liver disease." (PMID 41451371, 2025).
adenoma (1 paper, 2024). A neoplasm arising from the epithelium. "Several enzymes involved in NEAA biosynthesis were significantly regulated (highlighted in bold) in late-stage adenocarcinoma cells (M) in comparison to early adenoma cells (C1), such as upregulation of GPT and GLS2, and downregulation of GOT2 and GPT2." (PMID 39332495, 2024).
allergic asthma (1 paper, 2025). A asthma with a basis in a pathological type I hypersensitivity reaction. "We also found phenylpyruvate in the memory Teff and Treg cells, as well as upregulated expression of GOT1 and GOT2 in Th2 cells of allergic asthma patients, suggesting that they might be involved in faster turnover of Phe driving pathogenic Th2 cell activity." (PMID 41308641, 2025). "In addition, we noted that GOT1 and GOT2 were significantly upregulated in allergic asthma patients in Th2 cells." (PMID 41308641, 2025).
astrocytomas (1 paper, 2021). "The expression levels of GLUD1, GOT1, GOT2, and GPT2 were differentially expressed in astrocytomas compared to NN (p < 0.0001 Kruskal–Wallis test for GLUD1, GOT1, and GPT2 and p < 0.002 for GOT2)." (PMID 33910646, 2021). "Expression analysis of transcript coding for the key enzymes involved in glutaminolysis, GLSiso1, GLSiso2, GLS2, GLUD1, GOT1, GOT2, and GPT2 was performed in our series of astrocytomas of different malignant grades and NN brain samples." (PMID 33910646, 2021).
Burkitt lymphoma (1 paper, 2021). A rare form of malignant mature B-cell non-Hodgkin lymphoma. "The same has been observed for GOT2 at the mRNA level in Burkitt’s lymphoma Daudi cells and SUM159 cells as well as GOT2 protein in osteogenic sarcoma." (PMID 34503295, 2021).
Cerebral ischemia (1 paper, 2016). Restriction of arterial blood supply to the brain associated with insufficient oxygenation to support the metabolic requirements of the tissue. "With the docking design to galangin, the six proteins (GLUD1, GLUL, GLS, CTH, GOT2 and HP) with high affinity might become its targets for cerebral ischemia." (PMID 27058522, 2016).
deep vein thrombosis (1 paper, 2026). "Transcriptomic research revealed that, in comparison to the deep vein thrombosis (DVT) group, the expression of Got2 in the UC-MSCs group was markedly diminished." (PMID 41602836, 2026).
endotoxemia (1 paper, 2018). "For example, the aspartate aminotransferase Got2 was upregulated at advanced stages of endotoxemia which is closely correlated with liver damage." (PMID 29651289, 2018).
gastric ulcer (1 paper, 2014). An ulcerated lesion in the mucosal surface of the stomach. "The severely inhibition of TCA caused by the decreased of Got2 will contribute to formation of gastric ulcer." (PMID 24454691, 2014).
Hyperammonemia (1 paper, 2020). An increased concentration of ammonia in the blood. "However, in GOT2 deficiency, P5CS deficiency and GDH hyperactivity hyperammonemia is mild and does not result in glutamine excess." (PMID 31603991, 2020).
intrauterine growth restriction (1 paper, 2023). "Placental tissue from pregnancies with intrauterine growth restriction are exposed to high shear rates and showed also decreased glutamic-oxaloacetic transaminase 2, while GLUT1 was unchanged and glycolytic rate-limiting enzymes showed a trend to be upregulated." (PMID 37684702, 2023).
metabolic epilepsies (1 paper, 2023). "GOT2 deficiency is a mitochondriopathy that is reported to be implicated in treatable metabolic epilepsies." (PMID 37095366, 2023).
neuroendocrine tumors (1 paper, 2022). "The GOT2 mutation carriers are more susceptible to paragangliomas and pheochromocytomas, which are uncommon neuroendocrine tumors described as a strong genetic determinism." (PMID 35847355, 2022).
ovarian carcinoma (1 paper, 2024). A malignant neoplasm originating from the surface ovarian epithelium. "Moreover, the underlying mechanisms by which ALP and GOT2 are involved in ovarian cancer (OC) pathogenesis warrant further investigation through in-depth cellular and animal studies." (PMID 38915066, 2024).
renal angiomyolipoma (1 paper, 2023). "After applying Pearson analysis, we identified five proteins (out of the 34 intersected DE proteins) positively correlated with the maximum renal angiomyolipoma (p < 0.05), namely, PCSK1N, PMEL, HK1, GOT2 and SPTBN2." (PMID 36891236, 2023).
renal carcinoma (1 paper, 2022). A carcinoma arising from the epithelium of the renal parenchyma or the renal pelvis. "Therefore, we found that the HGD/GSTZ1-GOT1/GOT2 axis drives renal cancer cells to undergo aerobic glycolysis, converting uptake glucose into lactate to obtain energy to meet their own needs." (PMID 35562974, 2022). "At the molecular level, we found that SLC2A1, LDHA, GOT1, and GOT2 were regulated by HGD and GSTZ1 to alter the glucose uptake and energy metabolism of renal cancer cells." (PMID 35562974, 2022).
retinal detachment (1 paper, 2026). An eye emergency condition which may lead to blindness if left untreated. "Interestingly, GOT2, but not GOT1, is decreased in multiple models of PR degeneration, including retinal detachment (RD) where the NAD+/NADH ratio favors a reductive state." (PMID 41993491, 2026).
sarcoma (1 paper, 2020). A usually aggressive malignant neoplasm of the soft tissue or bone. "In addition, increased aspartate levels are in line with elevated expression of glutamate-oxaloacetate transaminase 2 (GOT2), the transaminase responsible for generating aspartate, in the sarcoma lines." (PMID 31980651, 2020).
Thiamine deficiency (1 paper, 2021). Thiamine deficiency is a condition that occurs due to not enough thiamine (vitamin B1). "Although the activities of GDH, OGDHC and NAD+-dependent IDH are not changed by thiamine deficiency in A549p21– cells, the level of GOT2 is increased 5-fold in the A549p21– cells, along with a small, but statistically significant upregulation of NADP+-dependent ME and IDH." (PMID 33868388, 2021).
tumor (75 papers, 2004 to 2025). "Tumor cells often upregulate GOT2 and associated metabolic pathways to enhance aspartate synthesis and uptake, thereby establishing metabolic competition with immune cells within the tumor microenvironment." (PMID 40842990, 2025). "GOT2 expression is often downregulated in HCC tumour tissues in IHC studies and associated with advanced disease progression and poorer patient prognosis." (PMID 41154605, 2025). "In vivo studies further demonstrate that the tumour-suppressive role of GOT2 in HCC is linked to its influence on glutamine metabolism." (PMID 41154605, 2025). "ASNS, GLS, and GOT2 encode ASNS, GLS, and GOT2, respectively, which are key enzymes in asparagine synthesis and are all required for tumor growth and metastasis, prompting the hypothesis that asparagine synthesis is required for SOX12-mediated CRC progression." (PMID 30858360, 2019). "However, in terms of Retcome pathways, overexpressed GOT2 was positively associated with tumor-related pathways, such as “MTOR Signaling” (NES = 1.44, adj. p < 0.001), “Cellular Response To Hypoxia” (NES = 1.647, adj. p = 0.004), “Signaling By NOTCH4” (NES = 1.661, adj. p = 0.007)." (PMID 37693904, 2023). "Abnormal GOT2 expression significantly alters the cellular response to senescence signals, and the resulting disruption of redox homeostasis directly impacts tumor cell proliferation and survival." (PMID 40842990, 2025). "After treatment with neutralizing antibodies against T cells, GOT2-silenced tumor growth was restored." (PMID 40247913, 2025). "Apart from its metabolic function, GOT2 also influences nuclear fatty acid metabolism and immune-related gene expression, affecting the tumor microenvironment." (PMID 40842990, 2025). "We found the increased expression of PFKP, TPX2, UBE2S, ST6GALNAC4, ADAM15, G6PD, and KPNA2, but decreased expression of GOT2 in tumor samples compared to normal samples." (PMID 40307857, 2025). "Taken together, STUB1 appears to be a strong suppressor, whereas GOT2 is a tumor oncogenic protein in BCa cells." (PMID 40651940, 2025). "In accordance with this view, GOT2-silenced tumor cells showed an increase in T-cell content, including CD4+ and CD8+ T cells, and a decrease in immunosuppressive Arg1+ macrophage abundance." (PMID 40247913, 2025). "The multicellular expression pattern and functional heterogeneity of GOT2 within the tumor ecosystem have been progressively elucidated." (PMID 40842990, 2025). "To further confirm the results, we also performed immunohistochemical staining of GOT2 in tissue microarray, including 35 samples of BCa tissues and 34 paired adjacent non-tumor tissues, which was used to stain of STUB1." (PMID 40651940, 2025). "By integrating metabolic and signaling roles, GOT2 supports tumor cell adaptation to stress, promoting growth, survival, and immune escape." (PMID 40842990, 2025). "GOT2 has been identified as playing a pivotal role in pancreatic cancer, modulating the immune microenvironment and suppressing anti-tumor immune responses." (PMID 38459595, 2024). "Among the GSE3189, GSE15605, and GSE114445 cohorts, the expression level of GOT2 was significantly higher in tumor tissues of CM than in adjacent normal skin tissues (all p < 0.05)." (PMID 37693904, 2023). "Based on a pan-cancer perspective, we initially demonstrated that GOT2 is differentially expressed in 18 tumor types, thus potentially being a therapeutic target." (PMID 35735610, 2022). "GOT2 was proven to be related to the metabolism of tumor cells, low GOT2 expression was detected in liver tumor tissues, and its downregulation was correlated with worse prognosis." (PMID 35924040, 2022). "Components of the amino acid metabolism such as SLC1A5 and GOT2 showed a similar behavior and were higher expressed in the Wnt‐high tumor entities." (PMID 35904277, 2022). "This further confirmed that the expression of GOT2 in tumor tissues was significantly lower than that in normal tissues." (PMID 35735610, 2022).
tumor (continued). "Increasing evidence has shown that dysregulation of GOT2 expression significantly influences tumor growth and the prognosis of several human neoplasms." (PMID 35735610, 2022). "While GOT2 KD induced some changes in tumor metabolite levels, the affected metabolic pathways were distinct from those observed in vitro, bearing in mind we were comparing homogenous cell lines with heterocellular xenografts." (PMID 35815941, 2022). "Contrastingly, different from CD4 + CAR-T cells, the conventional CD8 + CAR-T cells slightly increased the expression of CD98 and GOT2 after tumor challenge." (PMID 35869100, 2022). "Nevertheless, it was also reported that HIF-1α suppresses tumor cell proliferation in VHL-deficient renal cell carcinoma through the repressed aspartate-producing enzymes GOT1 and GOT2 and thus impaired oxidative and reductive aspartate biogenesis." (PMID 34858835, 2021). "All the hub genes except GOT2 were significantly downregulated in HCC tumor tissues compared with normal tissues (P < 0.001)." (PMID 33101029, 2020). "The tumour-to-blood (T/B) activity concentration ratio of GOT2-bearing mice is about 50, while some MTC patients have a much higher expression of SSTRs and consequently higher T/B values (up to 350 for 111In-octreotide) and can therefore benefit from PRRT." (PMID 32459817, 2020). "The in vivo xenograft mouse models using A549 cells also showed that downregulating miR-520a-5p or upregulating GOT2 restored the in vivo tumor growth ability of A549 cells after circ-SEC31A knockdown." (PMID 32499446, 2020). "Our study provides evidence that BRCA1 and ZBRK1 possess an additional role in tumor suppression, regulating the aspartate metabolism through transcriptional repression of GOT2." (PMID 30714292, 2019). "Because of the relatively low SSTR-expression in the GOT2 tumours, it would have been difficult to increase the absorbed dose by simply increasing the administered activity, due to tumour SSTR saturation." (PMID 31725814, 2019). "The model predicts that targeting GOT2 activity is a potential lethal approach to target glutamine metabolism to inhibit tumor growth." (PMID 28446878, 2017). "Clinical PDA cases expressing a high GOT1 to GLUD1 or GOT2 to GLUD1 ratio in the tumor have worse outcomes." (PMID 26462257, 2015). "GOT2 functions are dynamically regulated by post-translational modifications, including acetylation, phosphorylation, and succinylation, with modification patterns showing significant tumor type specificity." (PMID 40842990, 2025). "Additionally, GOT2 integrates metabolic and signaling pathways, enabling tumor cells to adapt to stress conditions and facilitating their proliferation, survival, and immune escape." (PMID 40842990, 2025). "further demonstrated that GOT2 knockdown reprograms glutamine metabolism by enhancing glutaminolysis, nucleotide biosynthesis, and glutathione production, maintaining redox balance and promoting tumor progression via the PI3K/AKT/mTOR signaling pathway." (PMID 40842990, 2025). "GOT2 is not only highly expressed in cancer cells but is also broadly expressed in immune cells (such as T cells and macrophages) and stromal cells (such as fibroblasts and endothelial cells) within the tumor microenvironment." (PMID 40842990, 2025). "GOT2 plays a particularly notable moonlighting role during malignant tumor progression." (PMID 40842990, 2025). "Tumor-type-based classification highlighting GOT2 regulation differences." (PMID 40842990, 2025). "demonstrating a dominant role of STUB1- GOT2 axis in controlling of in vivo tumor growth." (PMID 40651940, 2025). "Notably, in diffuse large B-cell lymphoma, inflammation-related signaling pathways (e.g., STAT3 and NF-κB) indirectly enhance GOT2 transcription by upregulating c-Myc, thus meeting the high metabolic demands of tumor cells." (PMID 40842990, 2025).
tumor (continued). "CAFs support GOT2-mediated metabolic reactions by secreting nutrient substrates such as glutamine, thereby facilitating the production of energy and biosynthetic intermediates in tumor cells." (PMID 40842990, 2025). "Disruption of GOT2 or MAS results in redox imbalance and impaired metabolic flux, which may cause neurological deficits or constrain tumor growth due to aspartate depletion and elevated oxidative stress." (PMID 40842990, 2025). "Paradoxically, GOT2 can also assume a tumor-suppressive role in certain oncogenic contexts." (PMID 38915066, 2024). "For example, SOX12, a tumour metastasis-promoting factor, promotes the formation of aspartic acid and eventually leads to tumour metastasis by upregulating various glutamine metabolic enzymes, including GOT2." (PMID 37829798, 2023). "GOT2 overexpression weakens the inhibition of tumour metastasis by SOX12 knockdown." (PMID 37829798, 2023). "The knockout of GOT2 weakens SOX12-induced tumour metastasis." (PMID 37829798, 2023). "Finally, low GOT2 expression resensitizes tumour cells to glutaminase inhibitors, to increase the effect of targeted glutamine on tumours." (PMID 37829798, 2023). "The mechanism by which GOT2 regulates glutamine metabolism in tumor cells may provide new insights into targeted therapy for CM." (PMID 37693904, 2023). "GOT2 knockout promotes haematogenous and hepatic tumour metastases." (PMID 37829798, 2023). "In addition to affecting glutamine metabolism, GOT2 promotes the metabolism of other amino acids and tumour metastasis." (PMID 37829798, 2023). "Interestingly, we found that the average methylation of all CpG sites (probes) near the TSS (transcription start site) of GOT2 was significantly higher in tumor tissues than in the normal counterpart (Aggregation, p = 0.00022)." (PMID 35735610, 2022). "In this study, we have found that HGD and GSTZ1 regulate the level of fumarate by metabolizing tyrosine, and by affecting GOT1 and GOT2 to coordinate amino acid metabolism and energy metabolism, determine the energy production pathway of tumor cells, and ultimately regulate the cell cycle." (PMID 35562974, 2022). "SIRT3 also inhibits tumor growth by deacetylating glutamic-oxaloacetic transaminase 2 (GOT2)." (PMID 36712965, 2022). "Besides this, it was shown that the AADAT and GOT2 enzymes that represent the ‘short branch’ of the KP leading to the KYNA formation presented expression levels below non-tumor tissue." (PMID 36355137, 2022). "Metabolic analysis reveals that CAFs provide tumor cells with pyruvate to overcome GOT2 dependency." (PMID 36230914, 2022). "In addition, another innovative aspect of this study clarified the significant correlations between GOT2 expression and various tumor-infiltrating immune cells in KIRC." (PMID 35735610, 2022). "Interestingly, blockage of pyruvate importation or pyruvate-to-lactate reduction cannot impair GOT2-depleted tumor growth, indicating hyperdynamic metabolic crosstalk in TME." (PMID 36230914, 2022). "Glutamate oxaloacetate transaminase 1 (GOT1) and glutamate oxaloacetate transaminase 2 (GOT2) are both crucial for promoting tumor progression by regulating glutamate metabolism because transaminases generate α-ketoglutarate and indirectly participate in the TCA cycle." (PMID 35757505, 2022). "GOT2 has been shown to be involved in the energy metabolism of tumor cells." (PMID 34035809, 2021). "Furthermore, high expression of hsa_circ_0002130 was found to inhibit tumor cell growth and promotes GOT2 expression." (PMID 34094907, 2021). "GOT2 is another mitochondrial enzyme involved in amino acid metabolism as well as the urea and TCA cycle; additionally, a germline mutation in the encoding GOT2 gene has been found in metastatic abdominal and thoracic PGL with a high succinate/fumarate ratio in tumor cells." (PMID 31362359, 2019).